IDH1 (isocitrate dehydrogenase (NADP(+)) 1)
Diseases named in the same sentence as IDH1 in open-access papers (continued):
Sharing a sentence is not in itself a finding about the gene and the disease.
glioblastoma (continued). "Similarly, in T98G glioblastoma cells treatment with ABT263 resulted in a significantly stronger anti-proliferative response among IDH1-mutated cells moving the respective IC50-values into the lower nanomolar range." (PMID 29057925, 2017). "Based on our observation that in IDH1-mutated glioblastoma cells Mcl-1 expression is decreased, we next examined whether 2-HG treatment would recapitulate this molecular feature." (PMID 29057925, 2017). "In summary, our work suggests that glioblastomas harboring an IDH1 mutation might benefit from the addition of a compound that efficiently interferes with Bcl-xL." (PMID 29057925, 2017). "IDH1-mutated U87MG glioblastoma cells showed a marked decrease in the mitochondrial membrane potential when subjected to treatment with increasing concentrations of ABT263 when compared to U87MG IDH1-WT cells." (PMID 29057925, 2017). "To confirm whether mTOR signaling is affected in IDH1-mutated glioblastoma cells, we performed western blot analyses for p-mTOR and its downstream effector p-S6." (PMID 29057925, 2017). "For example, in glioblastoma, mutated IDH1 produces abnormal 2-hydroxyglutarate." (PMID 29125844, 2017). "Available glioblastoma samples were also tested for the presence of IDH1 R132H and ATRX mutations." (PMID 29200599, 2017). "It was recently shown that IDH1-mutated glioblastomas may experience loss of heterozygosity, resulting in absence of wild-type IDH1 expression." (PMID 28074274, 2017). "Finally, we demonstrated that Bcl-xL inhibition is highly efficacious in several in vivo model systems of mutated IDH1, including an orthotopic xenograft model of glioblastoma and a patient-derived xenograft." (PMID 29057925, 2017). "Thus, our work suggests that elevated ECM stiffness can independently foster glioblastoma aggression and contribute to glioblastoma recurrence via bypassing the protective activity of IDH1 mutational status." (PMID 27820599, 2016). "Moreover, the combination of two biomarkers (IDH1 mutation and MGMT methylation status) outperforms either IDH1 mutations or MGMT methylation alone in predicting survival of glioblastoma patients." (PMID 27379174, 2016). "We hypothesized that PROX1 is a prognostic factor for patients with primary glioblastomas, the most common type of glioblastoma that arises in older patients and lacks IDH1/2 mutations." (PMID 27626492, 2016). "In 2008, the R132H IDH1 mutation was first found in human glioblastoma multiforme." (PMID 26812134, 2016). "The article confirms the hypothesis in astrocytoma/glioblastoma cell lines, in which exogenous expression of the mutated IDH1 results in a three- to 10-fold increase in temozolomide resistance after long-term passage." (PMID 27834917, 2016). "Initially, the review presents a brief overview on mutations commonly found in glioblastoma, and prunes the consequences of IDH1 mutation on glioblastoma biology to better understand the potential role of this particular mutation in the development of this tumor." (PMID 26858939, 2016). "IDH1 mutation is involved in >70% of astrocytomas, oligodendrogliomas, and secondary glioblastomas." (PMID 26338964, 2015). "Recently, it was discovered that most IDH1 mutant glioblastomas also have ATRX mutations." (PMID 26646075, 2015). "Concerning the 2 glioblastomas variant with PNET component, both were IDH1 positive, which suggest the possibility of secondary glioblastoma originated from this tumor or the different histogeneic origin of this tumor from the primary Glioblastoma." (PMID 27275230, 2015). "IDH1/2 mutations in long-term and non long-term survivors of patients with primary glioblastoma." (PMID 26158269, 2015). "By the time IDH1-positive tumours transform into glioblastoma, however, they may have acquired additional mutations that allow them to increase their proliferative capacity." (PMID 25849605, 2015).
glioblastoma (continued). "For example, IDH1 mutation has been reported to exert a greater prognostic relevance in glioblastoma and anaplastic astrocytoma than histological grade, indicating that molecular markers might potentially supersede histological grade in tumor classification." (PMID 26369702, 2015). "In fact, 96% of glioblastomas lack IDH1/2 mutations but show a strong 5-ALA fluorescence." (PMID 26008980, 2015). "IDH1/IDH2 mutations are known to be diagnostic molecular markers of secondary glioblastoma." (PMID 26143636, 2015). "Interestingly, the few primary glioblastomas with IDH1 mutations also have a significantly better prognosis." (PMID 27275230, 2015). "For example, WES analysis of glioblastoma multiformes led to the discovery of a previously unknown cancer-related gene, isocitrate dehydrogenase 1 (IDH1) that is recurrently mutated in glioblastoma multiformes." (PMID 26083936, 2015). "Subsequent multivariate analysis confirmed that IDH1 mutation may be an independent favorable prognostic marker in glioblastoma and anaplastic glioma after adjustment for other genomic profiles and treatment modalities." (PMID 26220714, 2015). "Additionally, we found mutations in IDH1 at codon 132 (2/42 cases), a hotspot for mutations in glioblastoma and intrahepatic cholangiocarcinoma, thus expanding the indications for IDH1 mutations." (PMID 25159915, 2014). "Similarly, the well-known mutation hotspot at R132 of IDH1 recurrent in lower grade glioblastoma (LGG) and AML is observed." (PMID 25484917, 2014). "Recent studies have highlighted VHL-deficient RCC and IDH1 mutant glioblastoma as particular genetic settings in which tumors may depend on GLS." (PMID 25502225, 2014). "Consistent with prior reports, G-CIMP+ glioblastomas all harbored the IDH1-R132H mutation." (PMID 25277177, 2014). "These lower grade lesions frequently progress according to the so-called clinical secondary glioblastoma pathway to grade IV lesions, and are strongly associated with mutations in the isocitrate dehydrogenase genes (IDH1, and rarely, IDH2), lower age of onset, and better prognosis." (PMID 23451042, 2013). "IDH1 positive glioblastomas were associated with a younger age at diagnosis, better clinical outcome, prominent oligodendroglial and small cell tumour cell morphology, pallisading necrosis and glomeruloid vascular proliferation in the absence of arcade-like structures." (PMID 23451042, 2013). "Primary glioblastomas with IDH1/2 mutations are very rare (<5%); show age distribution and genetic profiles similar to secondary glioblastomas, therefore could be misclassified." (PMID 24202337, 2013). "Of note, the group of young adult, IDH1 mutant tumours with these specific phenotypes may be functionally linked to a subset of paediatric glioblastomas driven by mutations in genes encoding the histone H3.3 variant." (PMID 23451042, 2013). "Less frequently, clinical de novo or primary glioblastoma may also be associated with young adults and IDH1 mutation, by which time the extensive microvascular proliferation associated with the higher grade tumours is already present." (PMID 23451042, 2013). "Tumor progression is accelerated via heterogeneous mechanisms including dysfunctional/deleted VHL gene in renal cell carcinoma and hemangioblastoma, inactivated IDH1 gene in glioblastoma, mutations in mitochondrial succinic dehydrogenases in paraganglioma, and others." (PMID 21949677, 2011).
glioblastoma (continued). "In U87-MG cells baseline levels of some VEGF isoforms under normoxia, mainly VEGF189 were high due to hypoxia-independent mechanisms as reactive oxygen species, NO, phosphatidylinositol-3-kinase and MAP kinase activation through the action of mTOR, or loss of IDH1 gene function in glioblastoma." (PMID 21949677, 2011). "D-2HG accumulates in glioblastoma cells with IDH1 R132H mutations." (PMID 21625441, 2011). "Interestingly, in an initial screen on 22 glioblastoma patients, mutations in the active site of IDH1 occurred in a large fraction of young patients and were associated with an increased overall survival in secondary glioblastoma patients." (PMID 19333441, 2009). "Another study using patient-derived glioblastoma cells xenografted into NCr nude mice has demonstrated that elevated extracellular matrix stiffness leads to glioblastoma aggression and thus promotes glioblastoma recurrence by bypassing the protective activity of IDH1 mutational status." (PMID 40940872, 2025). "In addition, MINK1 downregulated IDH1, which is associated with bad prognosis in glioblastoma." (PMID 39727954, 2024). "Therefore, PD-L1 immune checkpoint inhibitors analysis might not be advisable because of the globally low PD-L1 expression in patients with IDH1-mutant glioblastomas." (PMID 35741603, 2022). "However, the manner of IDH1 mutation regulating glioblastoma development was still unclear." (PMID 35488886, 2022). "Unruh and colleagues found that mutations of IDH1/2 are associated with increased methylation of the F3 (TF gene) promoter and decreased TF expression in glioblastoma multiforme (GBM)." (PMID 34359742, 2021). "In the present analysis, we evaluated the impact of MGMT promoter methylation as well as IDH1 mutation status on recurrence-free interval (the period from beginning of adjuvant therapy after surgical resection to the possible first date of recurrence) in patients with glioblastoma." (PMID 34257620, 2021). "IDH1 mutant status may be one of the decisive factors behind such relationship, because IDH1 mutation is frequently observed in diffuse gliomas but rarely seen in primary glioblastomas (WHO grade IV)." (PMID 34220689, 2021). "Analysis of primary brain tumours revealed a heterogenous G395A mutation in IDH1 (R132H) in 5 of 22 glioblastoma (GBM) patients with a further 3 GBM patients having the R132S variant." (PMID 34854890, 2021). "Several studies have shown that 75% to 80% of secondary glioblastoma (GBM) showed IDH1 mutations, whereas only 5% of primary GBM have IDH1 mutations." (PMID 34070746, 2021). "To further confirm that the detection of H–C3–H peaks of 2-HG is the marker of the IDH1-mutation status, we scanned intact IDH1-mutant and -wild-type xenografted tumors as well as intact human primary glioblastoma multiforme (GBM) tumors." (PMID 32587392, 2020). "In glioblastoma multiforme (GBM) Parsons and Colleagues identified specific heterozygous somatic point mutations in the isocitrate dehydrogenase 1 (IDH1) most often in R132." (PMID 33003334, 2020). "These mutations are also detected in grade IV glioblastoma (GBM), referred to as IDH1 mutant GBM, which account for ~10% of all grade IV clinical cases but are absent in pediatric high-grade malignancies and in nonglial subtypes of brain tumors." (PMID 32280672, 2020). "anaplastic astrocytoma cases had more MGMT promoter methylation (50%) than glioblastoma multiforme (GBM) (20%), more IDH1 R132H mutation (42%) than GBM (4.3%)." (PMID 33282092, 2020). "In addition to EGFRvIII, IDH1/2 mutations also play an important role in glioblastoma." (PMID 30777100, 2019). "Predictors of patient outcome derived from gene methylation, mutation, or expression are severely limited in IDH1 wild-type glioblastoma (GBM)." (PMID 31405148, 2019).
glioblastoma (continued). "Interestingly, in spite of the overall growth reduction, the colony forming capacity was enhanced in the IDH1R132H glioblastoma cell lines, indicating that the IDH1 mutation improves clonogenic survival, which might promote tumorigenesis." (PMID 31888244, 2019). "Notably, the NADPH production capacity is reduced in glioblastoma by 38% when IDH1 is mutated." (PMID 31242696, 2019). "In 2008, a multi-group collaboration found that IDH1 mutations occurred in 12% of glioblastomas, and subsequent researchers observed IDH1 mutations in 50–80% of LGGs and secondary GBM." (PMID 30061525, 2018). "One of the key molecular differences between primary and secondary glioblastoma is the presence of isocitrate dehydrogenase-1 (IDH1) mutations which are found in approximately 75% of secondary GBM but are rare in primary GBM." (PMID 30200436, 2018). "For example, a high HyperZ index was associated with BRAF in COAD and IDH1 in glioblastoma (GBM); both genes are linked to CIMP in cancer." (PMID 29125844, 2017). "Glioblastoma is the most fatal primary brain cancer, and IDH1 mutations are frequent in the progressive pathway to secondary GBM." (PMID 28948065, 2017). "Our study reveals that BRAF, H3F3A and IDH1 mutations are associated with distinct clinical features and can stratify young adult glioblastomas into prognostic subgroups, which have important clinical implications in refining the prognostic classification of glioblastomas in young adults." (PMID 26452024, 2016). "In a relatively short time after the discovery of IDH1 mutation in glioblastoma, a tremendous amount of work has been performed on the clinical relevance of this mutation regarding particularly its applications in the diagnosis, prognosis, and treatment of patients suffering from glioblastoma." (PMID 26858939, 2016). "Notably, although IDH1 mutation was identified in nearly 90% of secondary elderly glioblastomas, only 43% (3/7) of IDH1 mutation was detected in our young adult glioblastomas, suggesting that IDH1 mutation wasn't a main contributing marker for young secondary glioblastomas." (PMID 26452024, 2016). "Therefore we identified the IDH1 mutation in more than 45.4% of glioblastomas." (PMID 24511544, 2014). "Since polySia expression is significantly more common in IDH1 mutated tumors, and since these tumors have better overall prognosis, polySia may be a new additional molecular marker in the prognostic caharcterization of glioblastomas." (PMID 25164322, 2014). "The IDH1 mutations in glioblastomas were formerly identified predominantly in secondary GBM that progressed from the low grade tumors." (PMID 24511544, 2014). "A well-known relationship between the IDH1 mutation and DNA methylation was found by analyzing the mutation and DNA methylation Boolean implications in GBM, confirming known biology that IDH1 mutation produces hypermethylation in glioblastoma." (PMID 25054200, 2014). "In 2008, sequencing of glioblastoma multiforme (GBM) tumor samples identified IDH1 mutations at R132 (IDH1R132) in 12% of tumors." (PMID 23847760, 2013). "Given the heterogeneity of clinical glioblastoma specimens, we further correlated these data with tumour cell morphological subtypes, specific patterns of vascular proliferation and known genetic prognostic markers such as IDH1 mutation and MGMT promoter methylation." (PMID 23990986, 2013). "For example, mutations of the gene encoding isocitrate dehydrogenase 1 (IDH1) are very common in low-grade astrocytomas, anaplastic astrocytomas, oligodendrogliomas, anaplastic oligodendrogliomas, and secondary glioblastomas but very rare in de novo glioblastoma." (PMID 23862163, 2013). "In 2008, a novel mutation of IDH1 gene was firstly described in patients with glioblastoma multiforme (GBM)." (PMID 22397365, 2012). "Glioblastoma multiforme (GBM) sequencing analysis has shown recurrent mutations in isocitrate dehydrogenase 1 (IDH1) in 12% of patients." (PMID 19367275, 2009).
glioblastoma (continued). "Patients ≥65 years old with glioblastoma, IDH1/2-mutant astrocytoma, or oligodendroglioma had lower median survival compared to patients between 40–64 years and 20–39 years (all P ≤ .02)." (PMID 39164213, 2025). "Kagawa and colleagues have demonstrated that fatty acid-binding protein 7 (FABP7) is highly expressed in the nuclei of Isocitrate dehydrogenase 1 (IDH1) wild-type glioblastoma and promotes tumor proliferation by upregulating Cav-1 expression." (PMID 40243482, 2025). "A seismic shift in glioblastoma classification occurred based on the molecular biomarkers IDH1 (isocitrate dehydrogenase 1) and IDH2 (isocitrate dehydrogenase 2)." (PMID 40564017, 2025). "The data led us to conclude that the expression of IDH1 R132H sensitizes glioblastoma cells to ART-induced cytotoxicity." (PMID 40564198, 2025). "The MRI imaging, gross appearance, microscopic morphology, and pathological analysis of the tumour sample were consistent with the characteristics of IDH-1 wild-type glioblastoma." (PMID 40399275, 2025). "To this end, we have subjected patient-derived tumor cells from an R132C IDH1 mutant astrocytoma (grade III) patient (PD-AS) and an IDH1 wild-type (grade IV) glioblastoma patient (PD-GB) to label-free quantitative proteome profiling." (PMID 41009641, 2025). "Mouse xenograft models have shown that mutant IDH1 blocks glioblastoma aggression by reducing the HIF1α-dependent tenascin C expression to decrease extracellular matrix stiffness and mechanosignaling." (PMID 40940872, 2025). "Many authors created radiomics models for classification purposes of glioblastoma, in particular, for differentiating glioblastoma from brain metastasis or for predicting the molecular status of IDH1." (PMID 40075605, 2025). "Final pathology revealed glioblastoma (IDH-1) wildtype, O6-methylguanine-DNA-methyltransferase (MGMT) unmethylated CNS WHO Grade IV tumor." (PMID 41356860, 2025). "Specifically, FABP7 enhances caveolae/caveosome formation by inducing histone acetylation at the Cav-1 promoter, but only in IDH1 wild-type glioblastomas." (PMID 40243482, 2025). "In contrast, IDH1-mutant glioblastomas exhibit lower Cav-1 expression, reduced histone acetylation and decreased acetyl-CoA levels." (PMID 40243482, 2025). "Studies reveal that 10% of IDH1/2 wildtype glioblastoma tissues contain LRP1B deletions, significantly reducing expression in tumor samples compared to healthy tissue." (PMID 40564017, 2025). "Internal validation of multivariate models for glioblastoma, IDH1/2-mutant astrocytoma, and IDH1/2-mutant oligodendroglioma demonstrated relative consistency in model fit, with the greatest heterogeneity observed amongst IDH1/2-mutant oligodendroglioma models." (PMID 39164213, 2025). "This study focused exclusively on patients with newly diagnosed IDH1 wild-type glioblastoma to maintain cohort uniformity." (PMID 40149329, 2025). "The main goal of this study is to better understand how PD-L1 is expressed and interacts with IDH1 (R132H) within the glioblastoma tumor environment." (PMID 39906459, 2025). "The size of this cohort enabled us to elucidate rarer but significant molecular signatures, including 21q loss in glioblastoma as well as EGFR amplification and chromosome 22q loss in IDH1/2-mutant astrocytoma." (PMID 39164213, 2025). "It is worth noting that this study primarily focuses on the regulatory mechanisms of ferroptosis in IDH1 wild-type glioblastomas." (PMID 40399275, 2025). "Non-TCGA patients had significantly improved overall survival compared to TCGA patients, with 26.7%, 55.6%, and 127.8% longer survival for glioblastoma, IDH1/2-mutant astrocytoma, and oligodendroglioma, respectively (all P < .01)." (PMID 39164213, 2025).